HMGB1 (high mobility group box 1)
Diseases named in the same sentence as HMGB1 in open-access papers (continued):
Sharing a sentence is not in itself a finding about the gene and the disease.
cancer (continued). "HMGB1 and HMGB2 not only differently affect the cellular activity of telomerase in etoposide-untreated or -treated hESCs and hNECs, but the proteins also differentially modulate the sensitivity of cancer cells to distinct anticancer drugs." (PMID 33076532, 2020). "In this study, we demonstrated that recombinant human milk peptide lactaptin (RL2) induces death of cancer cells with ICD hallmarks in vitro with the release of ATP and high-mobility group box 1 protein (HMGB1) and exposure of calreticulin and HSP70 on the external cell membrane." (PMID 32560527, 2020). "Mechanistically, BOLD-100 has been shown to down-regulate GRP78 in thapsigargin-mediated stressed cancer cells and trigger immunogenic cell death through the PERK/EIF2a branch of the UPR accompanied by ROS production, release of high mobility group box 1 (HMGB1) and ATP secretion via autophagy." (PMID 32947941, 2020). "In particular, reduced HMGB1 activates autophagy, while its oxidized form induces apoptosis in neoplastic cells, suggesting that the HMGB1/TLR2 axis would be particularly active in promoting cancer growth in a reducing microenvironment." (PMID 33321934, 2020). "Binding of advanced glycation end products (AGEs), S100 proteins, high-mobility group box1 (HMGB1), amyloid β-peptide, lipopolysaccharides, β-sheet fibrils, advanced oxidation protein products, Mac-1, or phosphatidyl serine with RAGE directs the cancer cells toward survival and proliferation." (PMID 32443845, 2020). "Our findings verified that HMGB1 induced cisplatin resistance in HCC cells via HIF-1α, enriched the studies on the role of HMGB1 and HIF-1α in promoting cancer, and it will be interesting to further determine their synergism to induce cisplatin resistance in vivo." (PMID 32328193, 2020). "Moreover, the upregulation of HMGB1 and PCNA promotes the proliferation and migration of cancer cells." (PMID 32754037, 2020). "Our recent findings on the distinct modulation of cellular activity of telomerase by HMGB1 and HMGB2 could be a starting point for developing new approaches aiming at the promotion of cell death in drug-treated cancer cells." (PMID 33076532, 2020). "Overall, how acetylated HMGB1 differentiates MM from noncancerous conditions or from other cancers needs to be further explored." (PMID 30891101, 2019). "YAP and HIF-1α were primarily detected in the cytoplasm of cancer cells without HMGB1 treatment, while displayed distinct nuclear localization following rhHMGB1 treatment." (PMID 31558702, 2019). "Thus, both cancer cell lines stimulated with PS-PDT or PD-PDT induce emission of the three crucial DAMPs (CRT, HMGB1 and ATP), which points to the immunogenic nature of cell death." (PMID 31842994, 2019). "Then we speculate that HMGB1 may induce the expression of RAC1 and CDC42 followed by binding to TLR4, and activate PI3K/AKT signaling pathway, which plays an important role in cancer cell growth and malignant transformation." (PMID 30962261, 2019). "Finally, in some mesothelioma cell lines, ONCOS-102, an adenovirus that specifically targets cancer cells, is able to increase cisplatin-induced CRT exposure, ATP and HMGB1 release." (PMID 31861811, 2019). "In microenvironmental stress conditions, such as hypoxia, E-twenty-six transcription factor 1 and 2 (Ets1/2), and high-mobility-group protein B1 (HMGB1), mediate the upregulation Prdx5 in cancer cells, particularly in human prostate and epidermoid cancer cells exposed to H2O2 or hypoxia." (PMID 31500275, 2019). "We also found that N-S and rhHMGB1 treatment induced cancer cells to express cancer stem cell marker CD133, which can be inhibited by either silencing the HMGB1 gene in the secreting cells (HMGB1−/−-S group) or adding HMGB1 inhibitor in the supernatant (N-S + EP group)." (PMID 29615080, 2018). "HMGB1 is an abundant non-histone nuclear protein and considered as a central regulatory protein in cancer development." (PMID 29844348, 2018).
cancer (continued). "Much like autophagy, it is important to note that HMGB1 has both a positive and negative correlation in regard to cancer progression." (PMID 29666625, 2018). "Interaction of HMGB1 and TLR4 is involved in infection, tissue injury, and cancer." (PMID 30292233, 2018). "HMGB1 has been reported as a DAMP for immunogenic cell death (ICD) during chemotherapy and radiotherapy, and its release from necrotic cancer cells may activate the innate immune system to promote host anticancer immunity." (PMID 30258050, 2018). "Investigating immunogenic cell death markers in cancer cells infected with recombinant VVs, we demonstrated that all tested recombinant VVs were efficient in calreticulin and HSP70 externalization, decrease of cellular HMGB1, and ATP secretion." (PMID 28951871, 2017). "Cancer cells undergoing ICD expose calreticulin (CRT) on the outer leaflet of their plasma membrane followed by a sequential secretion of ATP and high mobility group box 1 (HMGB1)." (PMID 28695111, 2017). "Additionally, the interaction between HMGB1 and TLR4 mediates anti-cancer immunity during radio- and/or chemotherapy." (PMID 29246127, 2017). "ICD cannot be achieved by cancer cell death that is not accompanied by calreticulin exposure, ATP and HMGB1 release." (PMID 28060726, 2017). "HMGB1 released from hypoxic HCC cells could activate TLR-4 and RAGE signaling pathways, induce inflammation, and promote cancer invasion and metastasis." (PMID 26499944, 2016). "The HMGB1-mediated cell death was characterized by formation of giant mitochondria and a substantial decrease of ATP in HMGB1-sensitive (SW480) and HMGB1 partly resistant (HCT116) cancer cells, but not in HMGB1-resistant HT29 cells." (PMID 26948869, 2016). "High mobility group box 1 (HMGB1), which has become one of the most intriguing molecules in inflammatory disorders and cancers and with which ligand-activated peroxisome proliferator-activated receptors (PPARs) are highly associated, is considered as a therapeutic target." (PMID 27563308, 2016). "Surprisingly, the amount of HMGB1 released from cancer cells under normoxic conditions without glucose was higher than those values under anoxic conditions with or without glucose (anoxic data not shown)." (PMID 26979829, 2016). "Additionally, drugs currently used in cancer patients, including gemcitabine, taxol, Ara-C, doxorubicin, cisplatin, etoposide, and carboplatin, used at a dose of twice the IC50 which caused necrosis and cell death, could readily induce HMGB1 release within 24 h of treatment." (PMID 26469759, 2015). "HMGB1 was absent in the cytoplasm of the non-malignant gastric epithelial cells, whereas cytoplasmic HMGB1 was abundant in all four cancer cell lines." (PMID 25652880, 2015). "Our long-term follow-up of HMGB1-Tg mice over 1.5 years did not detect cancer or obvious neurological phenotypes (data not shown)." (PMID 25510912, 2015). "Although HMGB1 overexpression is observed in a number of malignancies, its role in cancer has not been fully elucidated." (PMID 25051367, 2014). "While three of the chimeras (ACTB->POTEM, ACTB->POTEE and SP100->HMGB1) have been found in normal population, three of the chimeras (C2orf27A->NBEA, HILPDA->EFCAB3, FARSB->TRIM61) were previously identified only in cancer samples." (PMID 25133550, 2014). "An anti-HMGB1 antibody or specific inhibitor (i.e. glycyrrhizin) or targeting its proposed receptors (RAGE and the toll-like receptor 4, TLR4) on cancer cells may prevent or inhibit the development of drug resistance." (PMID 25512109, 2014). "The effect of an HMGB1 neutralizing antibody on Dox resistance induced by extracellular HMGB1 from non-viable Dox-treated cancer cells or recombinant HMGB1 was also investigated." (PMID 25512109, 2014). "Moreover, recent studies reported that HMGB1 in rodent spinal cord dorsal horn and dorsal root ganglion (DRG) plays a critical role in several animal models of chronic pain including diabetic, cancer and neuropathic pain." (PMID 23991202, 2013).
cancer (continued). "All of these data suggests that CEA and HMGB1 are correlated with positive tendency in control subject, but does with negative tendency in cancer patients." (PMID 22496788, 2012). "Serum HMGB1 levels were significantly increased in patients with GC compared to those of patients without cancer." (PMID 19476625, 2009). "Although as a cautionary note, HMGB2 and HMGB3 are also upregulated in some cancers, and might play a role as RAGE activators in addition to HMGB1." (PMID 19292913, 2009). "Serum HMGB1 levels in subjects with cancer were significantly higher than the levels in those without cancer (p < 0.05), and the HMGB1 levels were also significantly greater in subjects in high-risk group compared to the normal group (p < 0.05)." (PMID 19476625, 2009). "The HMGB1/RAGE pathway plays a crucial role in this process, activating downstream pathways such as Ras/MEK/ERK1/2, microRNA, NF-κB, MAPK, and PI3K/Akt, thereby regulating molecular expression levels and promoting the progression and development of cancer cells." (PMID 41296391, 2025). "Moreover, although not in the cancer context, HMGB1 was shown drives upregulation of P-gp at the blood–brain barrier following cerebral ischemia via the related TLR4/NF-κB pathway." (PMID 41465435, 2025). "Currently, The mechanistic intricacies underlying the HMGB1-RAGE signaling pathway in oncogenesis remain incompletely elucidated, but the mechanism by which HMGB1 directly activates RAGE and plays a promotional role in a variety of cancers could be a potential research direction for cancer therapy." (PMID 40969278, 2025). "However, HMGB1 does not always promote cancer progression, and in some cases it appears to exhibit conflicting effects." (PMID 40969278, 2025). "Rather than treating HMGB1’s roles as separate phenomena, we highlight how its nuclear, cytosolic, and extracellular functions form a coordinated resistance network that enables cancer cells to withstand therapeutic stress." (PMID 41465435, 2025). "Notably, cancer cells undergoing ferroptosis release sufficient ATP and HMGB-1 to activate DCs within one to three hours, but not after 24 hours." (PMID 39842944, 2025). "ICD plays an important role in cancer immunotherapy.[6b] To investigate the induction of ICD by DMPtNPS and RT treatment, the ICD biomarkers‐calreticulin (CRT), adenosine triphosphate (ATP), and high mobility group box 1 (HMGB1) were analyzed by immunofluorescence and FCM analysis, respectively." (PMID 38063844, 2024). "Inhibition of HMGB1 and HMGB2 secretion and/or their activation of nuclear factor-kappa B (NF-kB) has potential utility for treating cardiovascular, and neurodegenerative diseases; whereas CT-HMGB2 could augment therapeutic approaches to cancer treatment." (PMID 38496553, 2024). "ENST00000311534 was significantly correlated with HMGB1, ENST00000326094 was significantly correlated with BTN3A1, CD160, TGFBR1, and IL6R, and ENST00000375991 was significantly correlated with CD276, ENTPD1, HMGB1, TLR4, KDR, and TGFBR1 among these 33 immune genes in more than 20 cancer types." (PMID 39766805, 2024). "After the confirmation of elevated HMGB1 mRNA levels in cancer cells (SCC-4, SCC-9, SCC-15, TCA-811 and CAL-27) in comparison with the neighboring non-cancerous tissues, further investigation was conducted on SCC-9 cell line as the one with the highest expression of HMGB1." (PMID 37511951, 2023). "Furthermore, it was reported that the oxidized lipid mediators, eicosanoids, ATP, HMGB1 and other signal molecules could be released into the TME by ferroptotic cancer cells." (PMID 36926345, 2023). "High amounts of HMGB1 cytoplasmic (mRNA) expression (with ensuing cellular release) were detected more often in basal-like or triple-negative breast cancers, than the hormonal and HER2 counterparts, with considerable pertinence to adverse consequences in patients with cancer." (PMID 37970208, 2023).
cancer (continued). "Thus, cell death cannot be sensed as immunogenic in the absence of HMGB1 in cancer cells or TLR4 in myeloid cells." (PMID 36429101, 2022). "Thus far, there are no publications reported on a multicancer analysis of HMGB1 in different cancer types." (PMID 36230798, 2022). "Importantly, these effects seem to be limited to cancer cells since none of the HMGB1 forms impacted the cellular viability or the metabolic activity of the C19 fibroblastic cell line." (PMID 35887213, 2022). "The results of the gap closure assay, performed to investigate the effects of HMGB1 on the invasion and metastatic behaviors of SW620 and SW480 cells in vitro, indicate that HMGB1 knockdown decreases the proliferation and migration capabilities of cancer cells compared with control groups." (PMID 36230798, 2022). "HMGB1 positively modulates multicancer-related pathways, e.g., extracellular HMGB1 increases the production of cytokines such as interleukin and interferon via NF-κ B, MAPK, and other pathways to promote cancer cells’ proliferation and growth, DNA replication and nucleotide excision repair." (PMID 36230798, 2022). "In adult GBM, immunocompetent mice that were vaccinated with early ferroptotic cancer cells that were induced by GPX4 inhibition exhibited more efficient phagocytosis and maturation of bone-marrow-derived dendritic cells (BMDCs), via the increased release of HMGB1 and ATP." (PMID 36145510, 2022). "The extracellular release of high mobility group box 1 (HMGB1) and adenosine triphosphate (ATP) attracts and activates antigen-presenting cells (APCs), and the translocation of calreticulin (CRT) on the surface of dying cancer cells serves as an “eat-me” signal to phagocytes." (PMID 33478072, 2021). "However, this study revealed a significant association between HMGB1 and VC, but not with FEV1, DLco, primary tumor size, cancer stage, and fluorodeoxyglucose uptake in cancer." (PMID 33980944, 2021). "The role of HMGB1 in filopodia formation during cancer metastasis has not been well-investigated." (PMID 33807275, 2021). "Spontaneous or therapy-induced cancer cell death promotes the release in the TME of danger signals favoring ICD, a kind of cell death represented by ATP release, exposure of calreticulin on cancer cell surface and extracellular release of high mobility group box 1 (HMGB1)." (PMID 34680425, 2021). "However, when PBP-primed cancer cells were co-incubated with NK cells, there was greater secretion of HMGB1 than observed with non-primed cancer cells co-incubated with NK cells." (PMID 34452238, 2021). "Furthermore, HMGB1 regulated DRP1 phosphorylation and increased mitochondrial fission and trafficking through the actin and tubulin cytoskeletal system to the filopodia leading edge in order to supply the energy for cancer cell migration." (PMID 33807275, 2021). "HMGB1 induces senescence via the CDK inhibitor p21 in the context of genotoxic stresses, such as Dox, camptothecin, and IR, and this mechanism could be applicable to drug-resistant cancer cells therapy." (PMID 33558529, 2021). "Activation of HMGB1/RAGE axis could induce the inflammation and lead to multiple types of cancer." (PMID 34369271, 2021). "High mobility group box 1 (HMGB1) is an important inflammatory mediator released from injured and death cells and believed to be endogenous danger signal for DNA repair, recombinant, cell death and apoptosis, which is responsible for multiple cancers and immune diseases." (PMID 33541260, 2021). "HMGB1 could activate the ERK1/2, MAPK, NF-kB and Akt signaling pathways by binding to the receptor for advanced glycation end products (RAGE), leading to the reprogramming of cancer cells." (PMID 33187536, 2020). "In addition, patients who had progressed to cancer also expressed weaker epithelial cytoplasmic HMGB1 in their background BO (absent + weak intensity in 67%) compared with patients who did not have malignancy (absent + weak intensity in 24%), p = 0.015." (PMID 31831860, 2020).
cancer (continued). "Although the role of the HMGB1-RAGE axis in cancer is not completely clear, HMGB1 is critical for directly activating RAGE or activating peroxisome proliferator-activated receptor gamma (PPAR-γ) pathway, and inhibiting HMGB1-RAGE activation, which might be a beneficial cancer therapeutic strategy." (PMID 32660524, 2020). "We demonstrate that changes in the expression intensity and location of HMGB1 are particularly relevant in pre-malignant oesophageal pathology and progression towards malignancy, rather than offering a discriminatory biomarker in cancer itself." (PMID 31831860, 2020). "Knockdown HMGB1 in the feeder cancer cells can not completely abrogate this effect." (PMID 31558702, 2019). "We have been investigating the relationship between the growth and migration of cancer cells and HMGB1/RAGE interaction in tumors, and recently we demonstrated that papaverine inhibits RAGE-dependent nuclear factor-κB activation, which is triggered by the RAGE ligand HMGB1." (PMID 31100066, 2019). "High-mobility group box 1 plays a pleiotropic role in inflammation and cancer progression and, hence, the interplay between TG2 and HMGB1 could be important for future applications in the field of cancer progression." (PMID 30691081, 2019). "OVs induce mostly immunogenic cancer cell death (ICD), which includes necroptosis, through exposure to calreticulin and the release of ATP, high-mobility group box 1 (HMGB1), DAMP, and PAMP, which may activate dendritic cells and incur adaptive antitumor immunity." (PMID 31122251, 2019). "Indeed, cancer cells succumbing to 8-MOP plus 4J UVA in vitro emitted key signals involved in the perception of RCD as immunogenic, including CALR exposure on the plasma membrane as well as ATP, HMGB1, and type I IFN release." (PMID 31371700, 2019). "Because cancer TMN staging remained unknown during patient randomization and could be determined only after surgery, this may explain the difference in baseline HMGB1 levels between the two study groups, because more patients in the DEX group had cancer at an advanced stage." (PMID 29853785, 2018). "Importantly, HMGB1 binds specifically to the major cisplatin-DNA adducts, 1,2-intrastrand d(GpG) and d(ApG) cross-links, which comprise 90% of the lesions, inhibiting repair of DNA damage by the NER and sensitizing cancer cells to cisplatin." (PMID 30402082, 2018). "Interestingly, higher level of HMGB1 was also seen in lung tumor tissue from PDX mice compared to that from normal mice (NC), which is consistent with previous reports indicating that HMGB1 is related to cancer progression." (PMID 29568761, 2018). "Novel strategies targeting HMGB1, such as glycyrrhizin, gabexate mesilate, ethyl pyruvate, and PPAR ligands that interfere with asbestos-mediated inflammation, may prevent or delay ARDs onset and relieve the progress of malignant ARDs." (PMID 28348451, 2017). "However, there is no information on HMGB1 levels in cancer patients treated with peptide vaccination." (PMID 28536706, 2017). "There are no ongoing clinical trials for HMGB1 targeted agents in patients with cancer so far." (PMID 28969092, 2017). "Distinctive features of immunogenic apoptosis include the cell surface exposure of calreticulin (CRT) and/or HSP90 in pre- or early-apoptotic stages, as well as the release of non-histone chromatin protein high mobility group box 1 (HMGB1) by cancer cells in late-apoptosis or secondary necrosis." (PMID 28435516, 2017). "High-mobility group box 1 (HMGB1) was found to be over-expressed in many kinds of human cancer, which binds with several receptors and activates RAGE-Ras-MAPK, Toll-like receptors, NF-κB, and Src family kinase signaling pathways and plays a crucial role in tumorigenesis and cancer progression." (PMID 26499944, 2016).